BDNF (brain derived neurotrophic factor)
Diseases named in the same sentence as BDNF in open-access papers (continued):
Sharing a sentence is not in itself a finding about the gene and the disease.
Obesity (continued). "Thus, further study about the roles of adiponectin and BDNF in obese status is essential for finding the regulatory mechanisms and therapeutic solution for obesity." (PMID 33375318, 2020). "Cross-sectional evidence in humans shows a negative gradient relationship between body mass index (BMI), glycemic control, and plasma BDNF such that lean, normoglycemic individuals had the highest plasma BDNF and people with obesity and type 2 diabetes (T2D) had the lowest." (PMID 33013465, 2020). "In this context, the common human BDNF Val66Met variant through reduction of the activity-dependent secretion and signaling of mature BDNF, is associated not only to neuro-psychiatric disorders and CVD but also to eating disorders and obesity in humans." (PMID 31405230, 2019). "The BDNF locus was also identified as a GWAS hit for obesity." (PMID 30242502, 2019). "A meta-analysis has revealed that the genes of pharmacodynamic targets of antipsychotics like HTR2C, DRD2, ADRA2A and genes implicated in obesity such as MC4R, GNB3, FTO, LEP, LEPR, BDNF, and INSIG2 seem to be consistently relevant to antipsychotic-induced weight gain." (PMID 32116676, 2019). "Activation of hippocampal insulin signaling by exercise might increase hippocampal neuroplasticity including BDNF and neurogenesis in the presence of obesity." (PMID 31311133, 2019). "In contrary, others showed elevated serum BDNF level in obesity." (PMID 30767081, 2019). "Similarly, studies have reported that exercise improves obesity-induced reduction in the hippocampal BDNF level." (PMID 31311133, 2019). "Overall, these studies report that adherence to a Mediterranean Diet and/or calorie restriction were associated with decreased DNA methylation in obesity-related genes such as PDK4, KCNQ1, WT1, SH2B1, FTO, BDNF, and PPARGC1A or inflammatory genes such as TNF-α." (PMID 31506096, 2019). "In animal models, the relationship between obesity and BDNF is quite robust and consistent." (PMID 30363954, 2018). "It has recently been suggested that BDNF may play an etiological role in obesity and metabolic syndrome via in utero “developmental programming” of the obesity and T2D phenotypes." (PMID 30363954, 2018). "Moreover, acting in the hypothalamus, and particularly through the receptor TrkB, BDNF can attenuate diet-induced obesity through a mechanism related to MC4R signaling." (PMID 29316939, 2018). "Finally, we evaluated the impact of the modulation of BDNF in the progression of diet-induced obesity and the integrity of the ME-SFI." (PMID 29316939, 2018). "The current meta-analysis is not able to find any association between BDNF levels, both in plasma and in serum, and obesity." (PMID 30081509, 2018). "Conversely, the immunoneutralization of BDNF in OR mice promoted body mass gain leading to increased adiposity, which was accompanied by increased caloric intake, therefore reverting the natural protection against diet-induced obesity in this subset of mice." (PMID 29316939, 2018). "Future studies should also assess how changes in quality of life and other indicators of psychosocial functioning relate to changes in BDNF and metabolic outcomes in response to an exercise intervention in clinical populations, such as adolescents with obesity." (PMID 30363954, 2018). "In addition, the immunoneutralization of BDNF was capable of transforming diet-induced obesity-resistant mice in obese-prone mice, which was accompanied by increased expression of inflammatory cytokines in the hypothalamus and increased leakage of the ME-BBB." (PMID 29316939, 2018). "Meta-regression models showed that cardiovascular (CV) risk factors (hypertension, diabetes, hyperlipidemia, and smoking habit) and demographic variables (male gender and age) did not influence the association between BDNF levels and obesity." (PMID 30081509, 2018).
Obesity (continued). "Likewise, the BDNF/tyrosine kinase receptor signaling pathway controls feeding and metabolism, and its dysfunction leads to severe obesity or subclinical inflammatory diseases such as metabolic syndrome, insulin resistance, and type 2 diabetes." (PMID 29997519, 2018). "First, we hypothesized that exogenous BDNF administration in the hypothalamus could protect OP mice from diet-induced obesity, whereas immunoneutralization of BDNF could increase diet-induced body mass gain of OR mice." (PMID 29316939, 2018). "Conversely, though other studies suggest that BDNF does not play an essential role in the regulation of energy expenditure 72, BDNF‐deficient mice show hyperphagia and consequent obesity." (PMID 29465826, 2018). "In conclusion, phyllodulcin is a potential sweetener that could be used to combat obesity by regulating levels of leptin, fat browning-related genes, and hypothalamic BDNF-TrkB signaling." (PMID 28934139, 2017). "Clinical characteristics of patients and controls, such as gender, antidiabetic and antilipid treatments, smoking history, and obesity conditions, may also have influence on altered BDNF levels." (PMID 29062839, 2017). "These novel findings provide important evidence that adiponectin may be possibly mediate the process of MC4R and BDNF involved in obesity." (PMID 28396685, 2017). "Previous cross-sectional studies have shown that plasma BDNF concentration is decreased in patients with type 2 diabetes and acute coronary syndrome, and it has also been reported to be correlated with obesity, blood pressure (BP), and lipid metabolism." (PMID 28575038, 2017). "Since TrkB is nearly exclusively expressed in podocytes in humans, BDNF may directly protect against podocyte injury under conditions such as obesity, diabetes, hypertension, and dyslipidemia, in addition to glomerular disease." (PMID 28575038, 2017). "Reports that plasma BDNF levels could be higher in some with obesity and DM can be attributed to the presence of resistance to the actions of BDNF or due to different methods employed in these studies." (PMID 28824543, 2017). "Further study is necessary to uncover the role of BDNF in pathological obesity." (PMID 28694523, 2017). "This may explain the involvement of BDNF not only in obesity and type 2 DM but also its role in depression and Alzheimer’s disease." (PMID 28824543, 2017). "In addition, we also prospectively examined the serum BDNF concentrations during OGTT in subjects with obesity following a body-weight reduction program." (PMID 27787389, 2016). "It has been reported that BDNF levels are low in obesity or patients with type 2 diabetes." (PMID 26740873, 2016). "In conclusion, an elevated BDNF AUC index but not fasting serum BDNF concentration was associated with obesity in our study." (PMID 27787389, 2016). "Neurotrophins, such as IGF-1 and BDNF, can mediate obesity's effects on cognition and behaviors." (PMID 26881095, 2016). "Moreover, hyperphagia and obesity observed in a subgroup of patients with WAGR syndrome has been attributed to deletions on chromosome 11 that induce haploinsufficiency of BDNF." (PMID 25825681, 2015). "The overlap between monogenic obesity genes and obesity genes identified via GWAS (e.g. MC4R and BDNF) might imply a role of hypothalamic dysfunction affecting the regulation of energy balance in polygenic obesity, which can drive T2D." (PMID 26363598, 2015). "At BDNF, our new lead SNP (rs4517468) was in moderate LD (r2 = 0.31) with the index variant (rs10835210) for the GIANT secondary signal of association for BMI at this locus, suggesting that they represent the same underlying effect on obesity." (PMID 26132169, 2015). "To test this hypothesis, we investigated expression of BDNF and TrkB by adipose tissue in a mouse model of dietary obesity and generated various conditional knockout (CKO) mouse models by using the Cre-loxP system." (PMID 28721258, 2015).
Obesity (continued). "Both BDNF and MC4R have previously been shown to be associated with obesity in other populations." (PMID 25760438, 2015). "BDNF mutant mice developed mature onset obesity, characterized by an increase in body weight." (PMID 25587547, 2014). "Meanwhile, only a limited number of human studies managed to correlate BDNF expression to obesity." (PMID 25386150, 2014). "Except for SNP rs925946 close to the BDNF gene, the obesity risk alleles of these SNPs were not consistent with the risk alleles associated with dysregulated glycemic traits." (PMID 25093408, 2014). "Additionally, a girl with obesity and impaired cognitive function who has only one functional copy of the BDNF gene has been described." (PMID 25122490, 2014). "In addition to its role in enhancing brain plasticity, BDNF has also been implicated in modulating brain energy metabolism, as evidenced by studies that demonstrate that perturbed BDNF signaling can manifest in metabolic disorders such as obesity." (PMID 24900924, 2014). "Obesity might be mediated through Sf-1 regulating activity of brain-derived neurotrophic factor (BDNF), an important regulator of energy balance in the ventromedial hypothalamus." (PMID 25122490, 2014). "In humans, two reports show a relationship between BDNF (locus 11p14) and obesity." (PMID 25122490, 2014). "However, brain- or hypothalamus-specific deletion or knockdown of BDNF induces overeating and obesity." (PMID 25309497, 2014). "Since mutations in the gene for TrkB, but not p75NTR, lead to obesity in humans and mice, BDNF should act on the TrkB receptor to mediate its effects on appetite and energy expenditure." (PMID 23519010, 2013). "Alcohol seems to be impacting BDNF and influence obesity among people living with HIV." (PMID 25089225, 2013). "The principal limitation of this study was the cross-sectional design, which does not allow us to make causal inferences between BDNF and risks of obesity." (PMID 25089225, 2013). "When BDNF signaling is compromised, neural circuits in these hypothalamic areas are dysfunctional and fail to transmit the anorexigenic signal of leptin, leading to leptin resistance and obesity." (PMID 23519010, 2013). "Low circulating levels of BDNF have been observed in individuals with both obesity and T2DM." (PMID 23431394, 2013). "In addition, 7 of the 17 (41.2%) GWAs-selected genes (FTO, TMEM18, INSIG2, FAIM2/BCDIN3, BDNF, SH2B1 and MC4R) were associated with obesity in this population." (PMID 23950976, 2013). "In addition, BDNF level in hypothalamus is altered in obesity and/or diabetes models such as db/db, agouti yellow and SF-1 knockout mice." (PMID 24106476, 2013). "In these studies, mice harboring a truncated long BDNF 3′UTR developed severe hyperphagic obesity." (PMID 23431394, 2013). "Loss-of-function mutations in BDNF or its receptor, tyrosine receptor kinase B (TrkB), have been associated with severe obesity and hyperphagia in both humans and mice, and studies in mice have shown that ablation of BDNF specifically in neurons is sufficient to induce obesity." (PMID 23700410, 2013). "Apart from those in FTO, several of the identified SNPs are located in or near genes clearly related to appetite regulation, and recently, five of the novel obesity loci (SH2B1, KCTD15, MTCH2, NEGR1 and BDNF) were indicated to be associated with dietary macronutrient intake levels." (PMID 23861046, 2013). "By contrast, heterozygous knock-out mice for BDNF showed hyperphagia and obesity." (PMID 23967328, 2013). "Central infusion of BDNF was reported to induce a severe and dose-dependent decreased appetite in rats and BDNF+/- mice were shown to exhibit chronic hyperphagia and related obesity." (PMID 24039946, 2013). "Brain derived neurotrophic factor, BDNF, regulates feeding, its expression is altered by consumption of high fat diet, and variants within the gene have previously been associated with obesity." (PMID 22781276, 2012).
Obesity (continued). "Moreover, obesity-related phenotypes have been described in heterozygous BDNF knockout mice as well as in mice in which the BDNF gene has been deleted selectively in excitatory neurons in the brain." (PMID 23028630, 2012). "Therefore BDNF is likely to mediate some of the beneficial effects of exercise with regard to protection against dementia, obesity, and type 2 diabetes." (PMID 22474595, 2012). "Interestingly some genes have been shown to be involved in both obesity and CNS disorders, such as neurotrophin BDNF and neurotransmitter CART." (PMID 22474595, 2012). "We have identified one new susceptibility locus for obesity near KCNMA1 (rs2116830) and confirmed association with BDNF (rs988712), by GWA analysis in a limited sample of morbidly obese and lean adults This study was followed up by genotyping of five additional European case-control cohorts." (PMID 21708048, 2011). "The BDNF rs4923461 A-allele associated with increased risk of overweight, with a per allele OR of 1.15 (1.07–1.24, p = 2.5×10−4), and borderline with obesity with a per allele OR of 1.14 (1.05–1.23, p = 0.002) but not with morbid obesity." (PMID 21912638, 2011). "The heterogeneity between cohorts for impact of BDNF rs988712 on obesity may be due to differences in ethnicity, age, or severity of obesity, as well as low power." (PMID 21708048, 2011). "Heterozygousknockout BDNF (BDNF+/-) mice exhibit metabolic abnormalities,hyperphagia, obesity, and insulin resistance that could be significantlyreversed by IF, indicating that BDNF is indeed involved in the beneficialeffects induced by IF." (PMID 20228939, 2010). "The results demonstrated that genetic variation in KCNJ11, BDNF, PFKP, PTER and SEC16B were associated with SGA and support the concept that genetic factors associated with obesity and/or type 2 diabetes are more prevalent in those born SGA compared to those born AGA." (PMID 20712903, 2010). "We have previously shown that BDNF regulates eating behavior and locomotor activity, and that BDNF+/- mice that accumulate approximately half the levels of the normal gene product throughout their body indeed develop aggressiveness, hyperactivity and obesity." (PMID 20025751, 2009). "In view of the reports documenting that BDNF+/- mice exhibit growth retardation, obesity, hyperactivity and aggressiveness, we felt it was critical to assess these parameters in our cKO mice that accumulate hippocampal BDNF to 50% of the levels observed in WT animals." (PMID 20025751, 2009). "Conversely, obesity may be due in part to the “supra-normal” levels of peripheral BDNF which over-activate the orexigenic TrkB signaling." (PMID 18382675, 2008). "In addition, a human case of hyperphagia and obesity was found to harbor a chromosomal translocation affecting BDNF expression." (PMID 18382675, 2008). "Important genes associated with monogenic obesity consist of leptin (LEP), leptin receptor (LEPR), proopiomelanocortin (POMC), prohormone convertase 1 (PCSK1), MC4R, single-minded homolog 1 (SIM1), brain-derived neurotrophic factor (BDNF), and its receptor NTRK2 (commonly referred to as TrkB)." (PMID 40428329, 2025). "Therefore, personalized exercise interventions may be necessary to optimize BDNF-mediated cognitive benefits in populations with obesity and T2D." (PMID 41277875, 2025). "Moreover, metabolic disorders like obesity and type 2 diabetes can alter BDNF expression, which in turn, may contribute to cognitive decline." (PMID 40565316, 2025). "Accordingly, we investigated whether any detrimental effects of high-fat diet (HFD)-induced obesity on cognition, motor behavior, adult hippocampal neurogenesis, and brain-derived neurotrophic factor (BDNF) could be mitigated by voluntary exercise training in male C57Bl/6 mice." (PMID 39871877, 2024).
Obesity (continued). "Future investigations should consider stratified analyses based on gender, allowing for a more nuanced understanding of how exercise-induced changes in circulating BDNF levels may differ between male and female participants, especially in the context of obesity." (PMID 38785805, 2024). "The reduced availability of functional BDNF might play an important role in obesity." (PMID 38534429, 2024). "However, the neural circuits responsible for the obesity and hyperphagia seen with defects in BDNF signalling are unknown." (PMID 39443799, 2024). "Furthermore, an increased BDNF level was linked to type II diabetes mellitus (T2DM) and obesity." (PMID 38362105, 2024). "Furthermore, the bidirectional relationship between NTFs and chronic disease may offer a therapeutic route for metabolic dysregulation, as increased BDNF levels may reduce obesity and diabetes." (PMID 38540381, 2024). "In addition, the expression of the fat mass and obesity-associated (FTO) gene has been found to affect hippocampal function and regulate BDNF processing, which helps to further explain the intricate relationship between RIF and BDNF." (PMID 38276070, 2024). "Therefore, future studies with age-stratified analyses could provide more nuanced insights into the relationship between exercise, circulating BDNF, and obesity." (PMID 38785805, 2024). "Given the intricate interplay between obesity, physical exercise, circulating BDNF, and neurological function, this study aims to systematically review and meta-analyze studies related to the effects of acute and regular physical exercise on circulating BDNF levels in individuals with obesity." (PMID 38785805, 2024). "Indeed, the brain-derived neurotrophic factor (BDNF), which is a protein that has a significant role in the energy homeostasis of body fluids and blood pressure in humans, registered significantly lower levels in the patients with obesity." (PMID 38785805, 2024). "Also, these results seem to support the hypothesis of a potential pathophysiologic mechanism of BDNF in obesity." (PMID 37548699, 2023). "In addition, identifying the mechanistic consequences of BDNF/TrkB signaling in resolving the relationship between obesity and BDNF could be an important step towards developing new treatment strategies for obesity and its associated medical complications." (PMID 37120612, 2023). "Therefore, BDNF and sirtuin 1 may mediate the association between the MC4R rs17782313 polymorphism and obesity as well as hyperglycemia, which requires further investigation to confirm." (PMID 37621650, 2023). "The present study showed a lack of association between BDNF levels and obesity and its phenotypes as measured by BMI and WC in Thai children; nevertheless, our findings are consistent with previous reports in a meta-analysis and in studies of Spanish prepubertal children." (PMID 37007871, 2023). "Furthermore, the exclusion criteria were selected to ensure exclusion of participants with disorders that could have an influence on the BDNF level, such as obesity or other neuropsychiatric disorders." (PMID 37786524, 2023). "Surprisingly, circulating BDNF concentrations in pediatric and adolescent patients were increased in autism spectrum disorders, decreased in Prader-Willi syndrome, increased in celiac disease, and similar to controls in children, adults and elderly with obesity." (PMID 37548699, 2023). "Because of our additional prior studies showing that hypothalamic BDNF mediates the improved metabolism and cancer outcomes in previous obesity and cancer EE studies, we hypothesized that TrkB signaling was also responsible for the outcomes we saw in the BTBR EE study." (PMID 36893171, 2023). "However, studies continue to identify new adipokines and myokines, such as nesfatin-1, neuregulin 4, myonectin, irisin, BDNF, decorin, visfatin, and chemerin, which may participate in the development of obesity-related diseases." (PMID 38136166, 2023).